IL5 (interleukin 5)
Diseases named in the same sentence as IL5 in open-access papers (continued):
Sharing a sentence is not in itself a finding about the gene and the disease.
asthma (continued). "TSLP which is the upstream role in the asthma cascade, inhibiting its stimulating activity on dendric cells and innate lymphoid cells thus preventing the induction of type 2 cytokines (e.g., IL-5, IL-4, and IL-13)." (PMID 34440488, 2021). "Biologics targeting eosinophilic inflammation have been successful for treating severe asthma, and several cytokines, including IL-4, IL-5, and IL-13, have demonstrated promising therapeutic effects in patients with COPD." (PMID 34829866, 2021). "In children affected by severe asthma biologics targeting IgE, IL-5 and against IL-4 and IL-13 receptors are already available, and they have also been applied in CRSwNP." (PMID 34943362, 2021). "New therapeutic monoclonal antibodies targeting the IL-5/IL-5 receptor pathway are extremely efficient in depleting blood eosinophils from subjects with asthma [...]." (PMID 34685594, 2021). "Anti-IL-5 therapy is now widely prescribed and often permits withdrawal of maintenance CSs in severe asthma." (PMID 34124538, 2021). "Some biologic agents, including anti-IgE and anti-interleukin-5 (IL-5), have been developed recently and used in the treatment of severe asthma." (PMID 33914833, 2021). "The activation of Th2 lymphocytes is a significant factor in the development of asthma, which can stimulate the synthesis of IgE and the infiltration of inflammatory cells by releasing representative cytokines such as IL-13, IL-4, and IL-5." (PMID 33628113, 2021). "Negative psychological stress has been found to increase the risk of asthma attacks in children, characterized by a high number of eosinophils in the sputum, EDN, IL-5, as well as decreased lung function during period of stress." (PMID 34055794, 2021). "High levels of CCL2 and CCL5 in the BALF along with increased IL-5 in patients with asthma induce eosinophil infiltration and activation." (PMID 33806085, 2021). "Th2 cytokines, such as interleukin-4 (IL-4), IL-5, and IL-13, can initiate and sustain important pathophysiological features of asthma." (PMID 33806085, 2021). "IL-4 is essential for the allergic response and immunoglobin E (IgE) production, and IL-5 is important for eosinophil survival and expansion, which contribute to lung injury in asthma." (PMID 33806085, 2021). "Th2 and ILC2-derived IL-4, IL-5, and IL-13 generate the typical pathophysiological effects of asthma, including activation and recruitment of eosinophils in the airways, IgE production by activated plasma cells, AHR and airway remodelling." (PMID 34020658, 2021). "We performed a retrospective analysis of patients with severe asthma and comorbid CRSwNP who were treated with anti‐IgE, anti‐IL‐5/R or anti‐IL‐4R." (PMID 34331521, 2021). "Currently available biologic therapies, including anti-IgE, anti-IL-5, anti-IL-5R⍺ and anti-IL-4R⍺, reduce asthma exacerbation rates in patients with Th2-high asthma." (PMID 33926084, 2021). "On the other hand, it is known that recruitment of Th2 cells that secrete IL-4, IL-5 and IL-13 accompanied by eosinophil recruitment to the airways has been considered integral to the pathogenesis of asthma." (PMID 33407843, 2021). "In patients with asthma, IL-5 is locally produced by Th2 lymphocytes, group 2 innate lymphoid cells (ILC2s), and epithelial cells in the airway mucosa." (PMID 35008504, 2021). "Th2-related cytokines, such as interleukin- (IL-) 4, IL-5, and IL-13, are important for the development of asthma." (PMID 34595240, 2021). "IL-33 is mainly secreted by the airway epithelium and evidenced to exacerbate the Th2-mediated inflammation via further promoting the secretion of IL-4, IL-5, and IL-13 in allergic patients with asthma." (PMID 32650472, 2020). "Inhaled corticosteroids are initially administered as controller medication for asthma, and biological preparations targeting IL-5/IL-5 receptor are used for some populations with corticosteroid-resistant asthma." (PMID 33292332, 2020).
asthma (continued). "Naïve T cells turn into Th2 cells, releasing a set of cytokines (IL-4, IL-5, and IL-13), which triggers the characteristic processes of asthma." (PMID 33488613, 2020). "ILC2 cells can promote the persistence of airway eosinophilia in patients with severe asthma through uncontrolled localized production of type 2 cytokines such as IL-5." (PMID 33292332, 2020). "Both in vitro and in vivo studies have demonstrated a strong link between TSLP expression and the production of IL-4, IL-5, and IL-13, which are central in the development of a T2 phenotype in asthma." (PMID 33255348, 2020). "Other than histamine, estrogen mediated production of IL-5 and IL-13 from mediastinal lymph nodes has also been observed in an animal model of asthma." (PMID 33574813, 2020). "Anti-IL-5 therapies, such as mepolizumab and benralizumab, are effective against eosinophilic airway inflammation and markedly reduce virus-induced asthma exacerbations." (PMID 32823491, 2020). "IL-5 stands out in the growth, differentiation, recruitment and survival of eosinophils, which are crucial in asthma inflammation and airway remodeling." (PMID 32600285, 2020). "Recently, the roles of IL-5 in the pathogenesis of eosinophilic diseases, such as eosinophil-dominant severe asthma and EGPA, have been established." (PMID 32326200, 2020). "Using multiplex xMAP technology, we have further validated that the levels of the upstream cytokines of S1P signaling such as IL-13, IFN-γ, TNF-α, IL-4, IL-5, and IL-1β were increased in the serum of asthma patients." (PMID 32637407, 2020). "Oral administration of WG or RG alleviated IL-4, IL-5, and IL-13 expression and immune cell infiltration in the bronchoalveolar regions of mice with ovalbumin-induced asthma." (PMID 32326081, 2020). "Clinical trials of biologic modifiers that block immunoglobulin (Ig) E, IL-5 or IL-4 receptor alpha (IL-4R alpha) subunit have demonstrated efficacy and safety in treating patients with uncontrolled severe asthma." (PMID 33352823, 2020). "The impact of biologicals on need of surgical procedures and presence of polyps and mucosal oedema in patients with comorbid severe asthma seemed to be milder in the anti-IgE group compared to patients receiving anti-IL5/IL5R therapy." (PMID 32467765, 2020). "Nevertheless, ginseng extracts alleviate allergic disorders such as asthma, allergic rhinitis, AD, and pruritus by inhibiting IgE, IL-4, and IL-5 expression through the modulation of mast cells, eosinophils, and Th1-to-Th2 ratio." (PMID 32326081, 2020). "Mepolizumab is a humanised monoclonal antibody that targets IL‐5 for the treatment of severe asthma with an eosinophilic phenotype." (PMID 32355562, 2020). "Although they are expensive, biologics such as anti-IL5 and anti-IgE agents promise cost-effectiveness when judiciously used to decrease asthma-related hospitalization and the debilitating side effects of systemic corticosteroids." (PMID 33352823, 2020). "Targeting IL-5 or its receptor has been shown to be a promising therapeutic approach for severe asthma." (PMID 32467785, 2020). "It is worth mentioning that silver NPs have been shown to mitigate asthma and decrease the levels of IL-4, IL-5, IL-13, and NF-κB in addition to lowering AHR in OVA-induced allergic inflammation mouse models." (PMID 32714326, 2020). "IL-5 is the main cytokine targeting eosinophilopoiesis, and the therapeutic efficacy of humanized monoclonal antibodies that target IL-5 and IL-5 receptor α for severe asthma has been established." (PMID 33292332, 2020). "This classification scheme differentiates Th2-high asthma, which is amenable to treatment with anti-IgE, anti-IL-5 or anti-IL-5Rα, and anti-IL-4Rα therapy, from Th2-low asthma." (PMID 32509793, 2020).
asthma (continued). "Maternal supplementation with B. breve M-16V during pregnancy and breastfeeding changed the composition of gut microbiota; some genera correlated with several features of asthma including mucin score and Th2 cytokines including IL-5 and IL-13 in lungs." (PMID 32915886, 2020). "Glucocorticoids are old anti-inflammatory drugs that have been shown to be very effective in treating asthma and can quickly inhibit the transcription of pro-inflammatory cytokines such as IL-2, IL-3, IL-4, IL-5, and IL-623." (PMID 32760206, 2020). "Although their usefulness against asthma can be limited due to redundant pathways, anti-IL-5 is promising, especially for hypereosinophilic syndromes." (PMID 33321726, 2020). "Commercially available humanized monoclonal antibodies target key cytokines of the allergic and eosinophilic pathways in asthma pathogenesis including immunoglobulin E (IgE), interleukin (IL)‐5 (IL‐5) and IL‐4/IL‐13." (PMID 31713955, 2020). "Mature ILC2 is known to produce Th2-type cytokines (IL-4, IL-5, IL-9, and IL-13) involved in the initiation of an adaptive immune response in asthma." (PMID 32395125, 2020). "IL-5 activity has been demonstrated to inversely correlate with pulmonary function in patients with asthma, and anti-IL-5 treatment has been shown to improve asthma control in patients with severe asthma and eosinophilia." (PMID 32328116, 2020). "Important target molecules of biological therapies of severe asthma in use today are the immunoglobulin E (IgE) molecule and the interleukin-5 (IL5) and IL5 receptor (IL5R) molecules." (PMID 32467765, 2020). "ILC2 is differentiated from ILC3 in response to activation of TLR2 and produces IL-5 and IL-13, which plays vital role in initiating and promoting immune response among asthma patients, and leads to the accumulation of eosinophils in BALF." (PMID 32600285, 2020). "It is well recognized that asthma is an immune response driven by Th2 and Th17 cells with cytokines such as IL-4, IL-5, IL-9, IL-10, IL-13, and IL-7 playing important roles." (PMID 33123005, 2020). "Immunological treatment with monoclonal antibodies against anaphylactic IgE or against type 2 cytokines such as IL-5 and IL-4/IL-13 is another way to control asthma symptoms." (PMID 32391011, 2020). "For instance, Th2 cells secrete cytokines such as IL-4, IL-5, and IL-13 and play important downstream roles in the pathogenesis of asthma." (PMID 32580518, 2020). "In this study, we examined the levels of IL-4, IL-5, and IL-21, which are involved in the pathology of asthma." (PMID 32143340, 2020). "The Th2 response plays a significant role in asthma, leading to interleukin-4 (IL-4), IL-5, and IL-13 production, IgE-mediated responses, mucus secretion and airway hyperreactivity (AHR)." (PMID 32620122, 2020). "This is consistent with the study of Han and colleagues who showed that immunization with mycobacterial antigens (Ag85 complex, MPB70 and 38-kDa) resulted in a significant increase in the IFN-γ:IL-5 ratio in the spleen compared to the asthma control group." (PMID 33101014, 2020). "It has been demonstrated that IL-33 receptor knockout decreases the airway inflammatory response but induces the persistence of IL-5+ IL-13+ type 2 innate lymphocytes to maintain certain characteristics of asthma." (PMID 32793232, 2020). "The upstream regulator cytokines of S1P signaling such as IL-13, IFN-γ, TNF-α, IL-4, IL-5, and IL-1β were significantly (P < 0.01) increased in the serum of asthma patients compared the healthy controls." (PMID 32637407, 2020). "Our findings show that OBE treatment resulted in a significant reduction of IL-4 and IL-5 consistent with other studies and effects of drugs that mediate an anti-allergic/anti-asthma action." (PMID 33123005, 2020). "In recent years, clinical drugs have been developed to improve the symptoms of asthma with potential therapeutic effects on IL-4, IL-5, and IL-13 expression levels." (PMID 32244835, 2020).
asthma (continued). "Interleukin 5 (IL-5) is a Th2 cytokine with a molecular weight of approximately 52 kDa that has also been shown to play an important role in the pathogenicity of asthma." (PMID 32467785, 2020). "Previous experiments showed that Majie cataplasm was an effective approach to mitigate asthma airway remodeling and had the potential to regulate Th2 cytokines of IL-5 and IL-13." (PMID 32489402, 2020). "All the asthma patients in the anti-IL5/IL5R group, except one, used high dose ICS as controller medication before receiving biological therapy." (PMID 32467765, 2020). "Along with TH2 cytokines, including IL-13 and IL-5, COX-2 has been implicated in asthma pathogenesis." (PMID 33022979, 2020). "In those cases where cortico-dependent asthma persists, despite inhaled triple therapy and monitoring of comorbidities, use of an anti-IL-5 should be considered after discussion in an Asthma Coordination Meeting." (PMID 33372616, 2020). "Altogether 55 asthma patients were included in the upper respiratory tract analysis, 38 patients receiving anti-IL5/IL5R therapy (mean age 54 years, 47% women) and 17 patients receiving anti-IgE therapy (mean age 48 years, 71% women)." (PMID 32467765, 2020). "The activation of ILC2 leads to the release of IL-9, IL-4, IL-13, and IL-5, and to Th2 type inflammation both in asthma and CRS." (PMID 33322143, 2020). "These phenomena are accompanied by Th2 cell activation and release of various cytokines (IL-4, IL-5, and IL-13) and chemokines (eotaxin), which are involved in the development of asthma." (PMID 32605045, 2020). "IL-5 has become a major target for both asthma and COPD due to the high proportion of patients with airway eosinophilia associated with disease severity." (PMID 33297418, 2020). "In this analysis, we included three patients in whom the indication for anti-IL5/IL5R therapy was nasal polyposis instead of asthma." (PMID 32467765, 2020). "Accordingly, IL-5 is associated to an enhancement of RSV associated-pulmonary disease and reported as a predictor of asthma, following severe RSV bronchiolitis in children under 2 years old." (PMID 32463330, 2020). "In the present study, we have focused on another type 2 cytokine, IL-5, which is also involved in asthma pathophysiology." (PMID 33644088, 2020). "In the lungs of patients with asthma, Th2 cells secrete excess IL-4, IL-5, and IL-13 to inhibit the expression of Th1 cells, which reduces IFN-γ secretion." (PMID 32244835, 2020). "The core project prioritised by the ISC for 2019 is the ‘Comparative effectiveness across severe asthma biologic classes (anti-interleukin-5 vs. anti-IgE targeted therapy) in patients eligible for both modalities’." (PMID 32819285, 2020). "The findings suggested that OVA exposure contributed to the remarkable elevation of IL-4, IL-5, IL-13, and IL-17A level in asthma group mice compared with control group mice." (PMID 33013383, 2020). "Accordingly, asthma induction also significantly decreased Treg-associated IL-10 and TGF-β production while significantly increasing Th2-associated IL-4, IL-5, and IL-13 production and Th17-associated IL-17 production (p < 0.05)." (PMID 33072079, 2020). "During asthma, there is a hyperactivity of Th2 responses, in which the cytokines of the type 2 immunity, such as IL-4, IL-5, and IL-13 promote the harmful inflammatory events in the airways." (PMID 33087044, 2020). "It has been reported that IL-5 levels in serum can be used as a biomarker for the blood eosinophilia asthma phenotype and that targeting IL-5 or its receptor alpha subunit (IL-5Ra) reduces eosinophil numbers and disease severity." (PMID 32467785, 2020). "It was reported that LA decreased the level of Th2 production of IL-4 and IL-5 in an asthma mouse model." (PMID 32719431, 2020). "Several currently available biological therapies for eosinophilic diseases including asthma target IL-5 or its receptor." (PMID 32466530, 2020).
asthma (continued). "In T2-high asthma, airway inflammation is driven by the release of interleukin-4 (IL-4), interleukin-5 (IL-5) and interleukin-13 (IL-13)." (PMID 33352823, 2020). "When relatively low levels of LPS are inhaled, a cascade of immune responses leads to Th2 cell induction, and IL-5 and IL-13 released by Th2 cells contributes to asthma development." (PMID 32203101, 2020). "On the other hand, increased IL-5 and submucosal eosinophilia have been found in the sputum of obese patients with severe asthma." (PMID 33134805, 2020). "Mepolizumab (monoclonal antibody against IL-5) treatment decreases exacerbations and enhances Asthma Quality of Life Questionnaire (AQLQ) scores in patients with eosinophilic asthma." (PMID 33321726, 2020). "Ginsan isolated from Panax ginseng reduced ovalbumin-sensitized IL-5 expression and airway hyperresponsiveness, remodeling, and eosinophilia in mice, resulting in the attenuation of asthma." (PMID 32326081, 2020). "In both therapy groups, the asthma control test (ACT) scores improved significantly (+ 4.5 scores in the anti-IL5/IL5R group and + 8.5 scores in the anti-IgE group)." (PMID 32467765, 2020). "In the eosinophilic phenotype of severe asthma, anti-IL-5 therapy enables reduction of asthma exacerbations and steroid use, better control of asthma and health-related quality of life, and improved lung function." (PMID 32150999, 2020). "Th2 cytokines, interleukin (IL)‐4, IL‐5 and IL‐13, drive major features of asthma, including increased eosinophils in the airway or bronchoalveolar lavage fluid, IgE class switching and airway hyper‐responsiveness." (PMID 32355562, 2020). "Although anti-IL-5 treatment and anti-IL-4/IL-13 treatment are clinically available for treating eosinophil-dominant severe asthma, recent research has been mainly focused on molecules that are more upstream, such as thymic stromal lymphopoietin." (PMID 32326200, 2020). "High IL-5 levels can be also detected in serum, especially when obtained from patients with severe asthma." (PMID 33329598, 2020). "Especially in severe asthma, IL-5-activated eosinophils also contribute to bronchial structural changes via the release of powerful pro-remodelling mediators such as transforming growth factor-β (TGF-β)." (PMID 33329598, 2020). "For instance, a study investigating the anti-inflammatory effects of a drug called alloferon in OVA-induced asthma in mice has shown decreased levels of IL-5 and IL-6 production, as well as decreased OVA-specific IgG1 but not OVA-specific IgG2a." (PMID 32392269, 2020). "IL-5 interacts with its receptor (IL-5Ra) expressed on eosinophils, maintaining airway inflammation and resulting in worsened asthma symptoms." (PMID 32467785, 2020). "In rat models with asthma, the treatment of NM showed a decreased eosinophil and neutrophil infiltration, and decreased levels of inflammatory factors such as IL-5, IL-6, IL-13, and IL-17 in bronchoalveolar lavage fluid." (PMID 31552177, 2019). "Placenta-derived MSCs exerted an anti-IL-5 effect and reduced IL-5 levels in an in vitro culture in different subgroups of the children with asthma." (PMID 31673233, 2019). "ST2+ memory CD4+ T cells have the capacity to produce high levels of IL-5 and Amphiregulin and are involved in the pathology of asthma." (PMID 30972065, 2019). "The exogenous administration of MaR1 (1 ng/mouse) to experimental animals during the allergic phase of asthma results in the decrease in eosinophils number in bronchoalveolar lavage, IgE, IL-5 and IL-13 levels and the increase in TGF-β concentration." (PMID 31216723, 2019). "IL-5 has been well established for its critical role in orchestrating inflammatory responses in allergic diseases, specifically asthma." (PMID 31697750, 2019). "Serum IL-31 levels were significantly elevated in patients with asthma and correlated positively with Th2 type cytokines IL-5 and IL-13, asthma severity or total serum IgE." (PMID 30647024, 2019).